CD4 (CD4 molecule)
Diseases named in the same sentence as CD4 in open-access papers (continued):
Sharing a sentence is not in itself a finding about the gene and the disease.
melanoma (continued). "We have demonstrated that immunization with a preparation of xenogenic placental extract induced a CD4-dependent immune response capable of inhibiting growth of B16 melanoma cells in the C57/BL6 mouse." (PMID 16725035, 2006). "TIL-2 phenotypes, measured by FACS analysis, showed a similar percentage of positive cells for melanoma and colorectal carcinoma with regard to CD4, CD8, CD56 and HLA-DR." (PMID 12610520, 2003). "Peptide-reactive CD4+ T cells also recognized HLA-DR4+ melanoma cell lines that constitutively express the relevant antigen." (PMID 11742496, 2001). "The present investigation studies a possible correlation between tumour-infiltrating CD4+ lymphocytes in malignant melanoma metastases and the therapeutic effect of biochemotherapy." (PMID 11747328, 2001). "The presence of CD4 + Th1 cells expressing IFN-γ in the TME is associated with beneficial clinical outcomes in patients with HER2 + breast cancer and other cancer types, including lung, colon, melanoma, and ovarian cancer." (PMID 41582199, 2026). "Moreover, immune cell deconvolution revealed a reduction of CD8+/CD4+ T cell infiltration in melanoma progression." (PMID 40722520, 2025). "Moreover, in human melanoma, infiltration of immune cells (i.e., CD8+ T cells, NK or CD4+ helper) into the tumour microenvironment is associated with improved survival and clinical response to immune therapies." (PMID 40898695, 2025). "It seems that melanoma cells may exhaust cytotoxic CD4+ T cells through recognition of HLA class II-restricted neoantigens, and also through HLA class I-restricted tumor-associated antigens." (PMID 40573917, 2025). "Therefore, harvesting RNA from CD4+T-cells and performing RT-qPCR on these DEGs, we are able to pre-determine the advanced or metastatic status of melanoma." (PMID 40226614, 2025). "CD4+ T FOXP3+ T regulatory cells are present in the primary melanoma TIME." (PMID 39825956, 2025). "A study on melanoma patients revealed that CD4+ T cells often recognize mutant neoantigens." (PMID 40636453, 2025). "αβ T cells: Studies have shown that γδ T cells can amplify the release of IFN-γ by αβ T cells (in B16 melanoma), presenting antigens to CD4+ T cells and cross-presenting antigens with CD4+ T cells to CD8+ T cells, thereby stimulating targeted immune reactions and exerting antitumor effects." (PMID 40558272, 2025). "However, CD4+ lymphocyte expression was significantly higher in lentigo maligna melanomas compared to other subtypes (H ═ 6.76, P ═ 0.034), with a mean value of 46% (95% CI: [1%, 59%])." (PMID 39976551, 2025). "Though further analysis revealed higher amounts of CD4+ T cells in groups with higher TLS levels, this contrasted with the UV-induced melanoma group that demonstrated a robust increase in CD4+ T cells, CD8+ T cells, B cells, and dendritic cells in cell-rich TLSs." (PMID 40940789, 2025). "Moreover, recent advancements have yielded increasing evidence supporting the pivotal role of IL-9 production by CD4+ T helper cells (Th9) in mediating anti-tumor immunity, particularly in melanoma." (PMID 40248207, 2025). "While activation-induced cell death and in vitro suppressive activity of Treg cells were not affected, ATG5 deficiency in CD4+ T cells led to increased anti-tumor responses against melanoma." (PMID 40977681, 2025). "In addition, we found that CD4+ T cells, isolated from peripheral blood mononuclear cells (PBMCs) of healthy donors, are more efficiently recruited by SkMel28 male melanoma cells in vitro, compared to female A375P cells." (PMID 39888245, 2025). "And c-Rel activity in CD4+ T cells could restrict their anti-tumor responses and promote its differentiation into Tregs and chemical c-Rel inhibition could reduce melanoma growth, suggesting c-Rel might harm CD4+ T immune response." (PMID 39998561, 2025). "CD4+ T cells appear to be less numerous than CD8+ T cells in the melanoma TIME." (PMID 39825956, 2025).
melanoma (continued). "In CD4+ T cells, only the Melanoma and the Notch signaling pathway were enriched." (PMID 40888231, 2025). "The observed increase in IL-2 levels among melanoma patients treated with Nivolumab is likely attributable to activation and expansion of CD4+ helper T cells and CD8+ cytotoxic T lymphocytes, which are principal producers of IL-2 following T-cell receptor engagement." (PMID 41020868, 2025). "Specific pathways and marker genes in the peripheral CD4+T-cells may predetermine melanoma staging and immunotherapy resistance." (PMID 40226614, 2025). "Moreover, T-sEVs derived from activated, antigen-specific CD4 T cells, potently suppressed anti-tumour cytotoxic responses in the animal model of melanoma." (PMID 40560407, 2025). "This is the first report suggesting that melanoma staging may be detectable by analysis of the peripheral CD4+T-cell profiles." (PMID 40226614, 2025). "The subsequently releaseddamage-associated molecular patterns (DAMPs) could stimulate humandendritic cell maturation and induce melanoma antigen-specific CD4+ and CD8+ T-cell responses, thereby enhancing antitumorimmunity." (PMID 39862206, 2025). "CD4+ FOXP3+ T regulatory cells may make up a higher proportion of the CD4+ T cell compartment in melanoma compared to normal skin." (PMID 39825956, 2025). "Consistent with reports in human melanoma and head and neck cancer, our analysis suggests that CD4 TILs exhibit altered transcriptional profiles suggestive of activation and exhaustion relative to their circulating CD4 T cell counterparts." (PMID 39932553, 2025). "Furthermore, we show that CD4+ T cell responses that are provided by the AAV capsid are crucial for effective murine melanoma treatment." (PMID 40671675, 2025). "CD4+ T cells are crucial in melanoma for their direct contribution to tumor control." (PMID 40636453, 2025). "CD4+ T cells that have cytolytic functions against tumors have been well studied in melanoma." (PMID 41228297, 2025). "Therefore, the basis of this study was the analysis of CD4+ T helper subsets in the peripheral blood of melanoma patients, as well as T-cell-specific cytokine profiling." (PMID 38539560, 2024). "However, in a study that looked only at melanoma metastases inside the SLN and visually counted intratumoral cells, greater CD4+ TIL counts were substantially linked with improved OS and RFS." (PMID 39712007, 2024). "Furthermore, strong suppression of melanoma growth was observed in WT mice with antibody-mediated CD4 T cell depletion in vivo." (PMID 39470607, 2024). "Melanoma_D_PBMC had similar patterns of CD4 and CD8 expansion." (PMID 38649520, 2024). "Superficial melanoma cases showed a predominance of CD4+ cells in all nine cases." (PMID 38673920, 2024). "Interestingly, in a murine model of implanted melanoma, neutrophils mediated tumor eradication by melanoma-specific CD4+ T cell therapy in combination with OX40 co-stimulation or CTLA-4 blockade." (PMID 39126091, 2024). "Similarly, patients with melanoma experiencing ipilimumab-related colitis tend to have a high level of CD4+ T-cells (P = 0.053) and a low proportion of regulatory T-cells (P = 0.018) at baseline." (PMID 38183211, 2024). "Blocking the PDPN + LNSCs by LTbR-Ig could increase the infiltration and proliferation of CD4 + TILs and inhibit melanoma development." (PMID 38167452, 2024). "The simulations propose that IL-6 secreted by high-E2F1 melanoma cells is sufficient to trigger the activation of the IL-6/IL6R/STAT3 axis in CD4+ immune cells, which could also trigger secretion of other inflammatory factors." (PMID 39544930, 2024). "When an increased melanoma incidence is observed in specific subgroups, it is not necessarily linked to a decline in CD4 + T cell counts or overall immune suppression." (PMID 39609320, 2024).
melanoma (continued). "Furthermore, a study analyzing infused TIL products in melanoma patients receiving adoptive cell therapy revealed that neoantigen-specific T cell clones were predominantly CD4+ and displayed cytotoxicity." (PMID 39766316, 2024). "In clinical melanoma, CD4+ Th1/IFNγ was found as the biomarker of better prognosis." (PMID 38827732, 2024). "Some MAGE-specific Tregs that were isolated from melanoma patients vaccinated with MAGE were CD4+CD25+ and demethylated FOXP3, whereas other CD4+ clones lacking CD25 could also suppress Teff cells, despite FOXP3 being methylated." (PMID 38891073, 2024). "Also, the coculture system indicates that IL-6 secreted by melanoma cells to the tumor niche activates in a paracrine manner CD4+ cells in their vicinity." (PMID 39544930, 2024). "Notably, the cDC population identified in our melanoma model resembles the cDC2 subset, which is specialized for priming of anti-tumor CD4 + T cell immunity." (PMID 39090759, 2024). "Additionally, in melanoma patients with FASN mutations, the immune cell infiltration levels of initial B cells, CD4+ T cells, cytotoxic cells, effector memory CD4+ T cells and DCs were enhanced." (PMID 38272906, 2024). "Notably, the neutrophil abundance was the highest in BC brain metastases, while CD4+/8+ T-cells were abundant in brain metastases from melanoma, which was the possible reason for the definite effect of immunotherapy on melanoma." (PMID 38649887, 2024). "Moreover, tumor-infiltrating type I T helper (Th1)-like CD4+ T cells are able to elicit cytotoxicity against B16 melanoma, indicating the potential of CD4+ T cells to directly target and eliminate tumor cells." (PMID 38673829, 2024). "In addition, we analyzed the percentage of Foxp3-expressing CD4+ T cells infiltrating B16 melanoma tumors in these mice." (PMID 39272810, 2024). "Furthermore, our data point to a dynamic crosstalk between melanoma and CD4+ T cells leading to E2F1-dependent perturbations in the immunoregulatory transcriptome of both cell types." (PMID 39544930, 2024). "In addition, single-cell profiling identified specific CD4+ T cell subsets that are enriched in melanoma patients who respond to ICI therapies as compared to those who did not." (PMID 38673829, 2024). "In addition, we simulated the effect of IL-6 secreted by melanoma on CD4+ T cells present in the TME (right)." (PMID 39544930, 2024). "Moreover, DTH biopsies from responder melanoma patients included a high proportion of CD4+CD45RO+ and CD8+CD45RO+ memory T cells, indicating that TAPCells vaccination can induce detectable cell-mediated immune responses after treatment discontinuation." (PMID 38675738, 2024). "CD4+ T cells coexpressing chemokine (C-X-C motif) ligand (CXCL)-13 (CXCL13) and cytotoxic genes are associated with a significantly prolonged overall survival (OS) time in melanoma patients." (PMID 38515134, 2024). "However, it is possible to sensitise poorly immunogenic tumours prior to administration of OX40 agonists by intratumoural CD4+ lymphodepletion, as has been shown in melanoma." (PMID 38809883, 2024). "For example, the melanoma patient‐derived immune organoids, embedded in collagen gel or Matrigel, contain multiple immune cells, including CD4+ T cells, CD8+ T cells, regulatory T cells (Tregs) and myeloid cells, and display immunosuppressive TME as the parental melanoma tissues." (PMID 39245957, 2024). "The E2F1-STAT3/IL-6 axis strongly modulates the immune niche and generates a crosstalk with CD4+ cells resulting in transcriptional changes of immunoregulatory genes in melanoma and immune cells that is indicative of an inflammatory and immunosuppressive environment." (PMID 39544930, 2024). "Interestingly, BRAF-mutant metastatic melanomas have increased CD4+ T cells and B cells but reduced CD8+ T cell infiltration versus BRAF wild-type samples." (PMID 39582535, 2024).
melanoma (continued). "We previously reported the identification of a subset of patients with advanced melanoma who developed hepatitis after Ipi-Nivo therapy, which was reliably predicted by cytomegalovirus (CMV) associated expansion of CD4+ effector memory T cells (TEM) cells prior to immunotherapy." (PMID 38926389, 2024). "To evaluate the significance of the direct effect of CXCL10-Fc on the ability of CXCR3+ CD4+ T cells to limit tumor growth, we performed an adoptive transfer in which CD4+ T cells were isolated from OT-II mice engrafted with Ret melanoma, transferred into CXCR3KO mice." (PMID 39474427, 2024). "In a melanoma mouse model induced by subcutaneous injection of B16 cells, activating nociceptors has been found to enhance the recruitment of NK, CD4+, and CD8+ T cells, which exhibit a less exhausted phenotype with reduced PD1 and cytotoxic T-lymphocyte-associated protein 4 (CTLA-4) expression." (PMID 38433844, 2024). "In a B16 melanoma mouse model, CD11b+ DCs—the homolog of cDC2s in humans—infiltrate the tumor site but display a reduced antigen presentation capacity through MHC-II, causing a weak activation of CD4+ T-cells in lymph nodes." (PMID 37190135, 2023). "Furthermore, in a tumor-bearing mouse model, it was demonstrated that EVs secreted by CD4+ T cell attenuated the growth of melanoma significantly via CD8+ T cell mediated tumor suppression." (PMID 37575250, 2023). "Of note CSPG4-reactive CD4+ T cells have been identified in melanoma patients before." (PMID 37849763, 2023). "To explore a direct role for LKB1-deficient DCs in promoting Th17 responses, we sorted hepatic cDC2s, the main CD4+ T cell–priming subset shown to induce Th17 priming, from lean CD11cWT and CD11cΔLKB1 mice that were s.c. injected with Flt3L-secreting B16 melanomas to expand the in vivo DC pool." (PMID 37140993, 2023). "Furthermore, the expansion of CD4+ naïve T cells to CD4+ CM T cells after ICI therapy predicted long-term survival benefits in patients with malignant melanoma." (PMID 37638022, 2023). "In addition, tumor‐specific cytotoxic CD4+ T cells express lytic granules induced by Eomes after ipilimumab treatment in patients with advanced melanoma." (PMID 37829505, 2023). "To identify melanoma proteins that contributed to fucosylation-triggered, CD4+ T cell-mediated melanoma suppression, we subjected fucosylated proteins from human melanoma cells to liquid chromatography–mass spectrometric (LC–MS/MS) analysis followed by Ingenuity Pathway Analysis21 (left)." (PMID 36690875, 2023). "Further, the phenolic compound named gallic acid synthesized conjugated with NLG8189 has shown a clear immunomodulatory action in melanoma setup, regulating the CD4+/CD8+ ratio and the number of Treg cells, as well as significantly inhibiting melanoma growth both in vitro and in vivo." (PMID 36768978, 2023). "However, there is an expansion of a population of BDCA1+CD14+ cells (possibly corresponding to DC3s) expressing PD-L1 in melanoma patients, which can be found in DC vaccines, and responsible for suppressing CD4 T-cell responses." (PMID 37190135, 2023). "Additionally, a study on B16 melanoma revealed that IL-21+ CD4 T cells induce a greater than 2-fold increase in CX3CR1+CD8 TILs." (PMID 38328405, 2023). "Using melanoma-derived cell lines and primary CD4+ CD25- T cell co-cultures, Rad Pour and colleagues demonstrated that activation of CD4+ T cells results in increased production of IFNγ with concomitant increases in Kyn and kynurenic acid that is attributed to reduced KMO expression in CD4+ T cells." (PMID 37876966, 2023). "Therefore, our results reveal a role of blood circulating CD4+CD26high T cells as potential biomarkers to predict the anti-PD-1 response in melanoma patients." (PMID 37170241, 2023).
melanoma (continued). "Co-cultured with peptide-pulsed monoallelic HLA class I-expressing targets, TCR-transduced CD4+ effectors recognized their cognate antigens within HLA class I restriction, suggesting that the HLA class II positive melanoma TME is rich in neoantigen-specific Treg cells." (PMID 36646683, 2023). "The pDCs activated and pulsed with tumor peptides—delivered to melanoma patients through intranodal injection—could migrate to the lymph nodes where they efficiently activated anti-tumor CD4 and CD8 T-cells." (PMID 37190135, 2023). "The function of MHC-II expression in tumor cells has long been unknown; recently, several studies have demonstrated that CD4 T cells can recognize melanoma cells in an antigen-specific, MHC class II-dependent manner." (PMID 38299143, 2023). "Moreover, TCR engineered BRAFV600E‐specific CD4+ T cells have been reported to enhance the CD8+ T cell response in patients with melanoma and induce an antitumor effect." (PMID 37829505, 2023). "In addition to inhibitory receptors, CD4+ T cells in TME exhibited poor effector function in a murine melanoma model." (PMID 37829505, 2023). "The melanoma antigen Trp1 exists in the plasma membrane, which may facilitate direct presentation to CD4+ T cells by B16 tumor cells." (PMID 36512410, 2023). "A study of patients with melanoma showed that CD4+ T cells frequently recognize mutant neoantigens." (PMID 38328405, 2023). "In addition, the relationship between the expression of ITGAL and CD4+ CD8+T cells in melanoma tissue sections was studied by multiple immunofluorescence staining." (PMID 37388230, 2023). "More recently, CD4 CTL clusters have also been identified in melanoma and other tumor types." (PMID 37185301, 2023). "Intense characterization of tumor antigen-specific CD4+ CTL was carried out also in melanoma." (PMID 37965314, 2023). "The Flt3-L treatment bolstered CD141+ DC numbers, leading to potent antigen-specific CD4+ and CD8+ T cell responses in vivo, which caused the regression of pre-established triple-negative breast cancer and melanoma tumors following CD141+ DC-targeting TNE vaccination." (PMID 37626903, 2023). "A third study later on demonstrated that melanoma control by TRP-1 tgTCR CD4+ CTL could also be improved when T cells were co-administered with an agonist antibody binding the costimulatory OX40 molecule." (PMID 37965314, 2023). "A previous evaluation of the T cell phenotype, by flow cytometry, in patients with stage IV melanoma or renal cell cancer treated with an anti-CTLA-4 reported an increased frequency of T cell subtypes such as CD4+, CD8+, CD4+CD25+, and CD4+CD25- that co-express the activation marker HLA-DR." (PMID 37631034, 2023). "Furthermore, we analyzed miR-155 expression levels in peripheral CD3+ cells, CD4+ cells, and CD4+ CD25+ cells from melanoma patients and compared them with healthy donors." (PMID 37197667, 2023). "Following batch effect correction, 26,161 cells were separated into 28 clusters and designated as melanoma cells, neural cells, fibroblasts, endothelial cells, NK cells, CD4+ T cells, CD8+ T cells, B cells, plasma cells, monocytes and macrophages, and dendritic cells." (PMID 37435067, 2023). "A previous report had documented that skin could become vitiligo after tumors were surgically removed when CD4+T cells, including CD4+Treg cells, were depleted with antibodies in a melanoma model." (PMID 37407600, 2023). "While transcriptomic signatures corresponding to cytotoxic CD4+ T cells have been identified in patients with melanoma and bladder cancer and direct tumor recognition by CD4+ T cells has been observed, studies also suggest that only a small subset of melanomas harbor any MHC-II+ cells." (PMID 37400675, 2023). "Consequently, EVs originated from CD4+ T cells are promising therapeutic agents to induce potent anti-tumor responses for melanoma patients." (PMID 37575250, 2023).